ZNF567-DT (ZNF567 divergent transcript)
Synonyms: formerly LINC01534
Gene: Long non-coding RNA gene on chromosome 19 (36,681,595 to 36,687,578, reverse strand). Ensembl gene ENSG00000225975.
Diseases named in the same sentence as ZNF567-DT in open-access papers:
ZNF567-DT is named in the same sentence as 3 diseases in open-access papers, as found by Europe PMC text mining. Sharing a sentence is not in itself a finding about the gene and the disease.
ZNF567-DT shares sentences with these, for which no sentence is quoted: cancer (1 paper); lymph node metastasis (1); tumor (1).